AHR (aryl hydrocarbon receptor)
Diseases named in the same sentence as AHR in open-access papers (continued):
Sharing a sentence is not in itself a finding about the gene and the disease.
esophageal cancer (6 papers, 2019 to 2024). A primary or metastatic malignant neoplasm involving the esophagus. "Compared with the other cancer types, the nuclear and cytosolic AhR expressions were significantly positively correlated in esophageal cancer." (PMID 38680496, 2024). "Our study demonstrated that miR-132-3p/CAND1/ZDHHC23 and miR-576-5p/AHR were critical molecular pathways related to the radiosensitivity of esophageal cancer." (PMID 36456979, 2022). "GEPIA database indicated that AHR expression levels were actually elevated in esophageal carcinoma (ESCA) compared with normal tissues." (PMID 32546278, 2020). "Furthermore, various studies have indicated the importance of AHR (aryl hydrocarbon receptor) in the occurrence and development of esophageal cancer, and further suggested AHR as a potential biomarker for esophageal cancer." (PMID 36456979, 2022). "Altogether, the miR-132-3p/CAND1/ZDHHC23 and miR-576-5p/AHR pathways could affect radiosensitivity in esophageal cancer." (PMID 36456979, 2022). "Finally, it was verified that miR-132-3p/CAND1/ZDHHC23 and miR-576-5p/AHR could affect the radiosensitivity in esophageal cancer." (PMID 36456979, 2022). "Additionally, our findings indicated that the miR-132-3p/CAND1/ZDHHC23 and miR-576-5p/AHR pathways could influence radiosensitivity in esophageal cancer." (PMID 36456979, 2022). "Collectively, findings obtained in the current in silico study provide evidence for the prognostic evaluation in esophageal cancer following radiotherapy by targeting the miR-132-3p/CAND1/ZDHHC23 and miR-576-5p/AHR pathways." (PMID 36456979, 2022). "Ultimately, 2 miRNAs (namely, miR-132-3p and miR-576-5p) and 4 mRNAs (namely, CAND1, ZDHHC23, AHR, and MTMR4) were obtained followed bioinformatics analyses, and possessed the potential to serve as prognostic biomarkers for radiosensitivity in esophageal cancer patients." (PMID 36456979, 2022). "The prognostic risk model based on 2 miRNAs (miR-132-3p and miR-576-5p) and 4 mRNAs (CAND1, ZDHHC23, AHR, and MTMR4) could accurately predict the prognosis of esophageal cancer patients." (PMID 36456979, 2022). "Furthermore, we uncovered that the prognostic risk model based on 2 miRNAs (miR-132-3p and miR-576-5p) and 4 mRNAs (CAND1, ZDHHC23, AHR, and MTMR4) could accurately and effectively predict the prognosis of patients with esophageal cancer." (PMID 36456979, 2022).
esophageal squamous cell carcinoma (6 papers, 2020 to 2024). Esophageal squamous cell carcinoma (ESCC) is a type of esophageal carcinoma (EC) that can affect any part of the esophagus, but is usually located in the upper or middle third. "It has been shown that AhR is highly expressed in patient-derived esophageal squamous cell cancers and correlates with poor overall survival." (PMID 38807762, 2024). "AhR was overexpressed in esophageal squamous cell carcinoma (SCC), and selective AhR modulation with DIM (3,3′-diindolylmethane) inhibited migration and invasion and downregulated the mesenchymal markers vimentin and Slug to suppress both EMT and metastases." (PMID 38339226, 2024). "Also, the elevated level of AhR is associated with lymph node metastases and/or poor prognosis in inflammatory breast and esophageal squamous cell carcinomas (ESCC)." (PMID 38361941, 2024). "High AHR expression also correlates with lymph node metastases and/or poor prognosis in inflammatory breast and esophageal squamous cell carcinomas (ESCC)." (PMID 33396563, 2020). "Studies in mice demonstrate that esophageal squamous cell carcinoma cells express TDO, which promotes tumor growth and induces monocyte differentiation into the pro-tumorigenic M2 macrophage via AhR." (PMID 38807762, 2024).
fungal infection (6 papers, 2017 to 2024). "Research indicates that the involvement of IDO and AhR is essential for the control of pulmonary fungal infection and the tolerance of mycosis." (PMID 38680494, 2024). "The precise mechanisms by which the AhR signaling pathway regulates the pathogenicity of fungal infections remain poorly understood." (PMID 38680494, 2024). "brasiliensis yeasts and groups of 5 animals were treated with the AhR agonists L-Kyn (800 μg i.p./mice) or FICZ (200 μg i.p./mice) every other day starting at day-1 of fungal infection." (PMID 33936043, 2021). "More recently, AhR has been shown to play a critical role in immunity by acting as an immune modulator during fungal infection." (PMID 29403477, 2017). "In fungal infections, the importance of the IDO-1/Kyn/AhR axis in the generation of Treg cells and tolerogenic activities of DCs was demonstrated." (PMID 32647342, 2020). "The AhR–IDO axis has been recently demonstrated in fungal infection, highlighting a role for IDO-derived metabolites to trigger AhR target genes." (PMID 29403477, 2017). "We found that the MC-SeCs but not the E-MCs promoted the expression of these AhR-dependent genes in colon fungal infection compared to the controls." (PMID 38534388, 2024).
glaucoma (6 papers, 2020 to 2025). Increased pressure in the eyeball due to obstruction of the outflow of aqueous humor. "In a study using the Adverse Outcome Pathway framework, the AHR is linked with glaucoma, including changes in the gene for CYP1B1." (PMID 35295218, 2022). "We also highlight that supplementation of relative endogenous metabolites aiming to refine intrinsic tryptophan metabolism and AhR signaling may be a more effective strategy to limit amplified inflammation associating local glial cells for glaucoma treatment." (PMID 36754954, 2023). "Taken together, these findings indicated that altered tryptophan metabolism and reduced tryptophan derived AhR ligands may cause insufficient retinal AhR activation in glaucoma." (PMID 36754954, 2023). "Here the protective role of tryptophan metabolites/AhR pathway limiting dysregulated local inflammation mediated by microglia in glaucoma were studied in detail." (PMID 36754954, 2023). "We aimed to modulate the intrinsic changes of tryptophan metabolism and AhR signaling that affect microglia activity to inhibit local inflammation in glaucoma." (PMID 36754954, 2023). "Results showed altered serum tryptophan metabolism and reduced retinal AhR expression in glaucoma patients." (PMID 36754954, 2023). "Taken together, these findings establish a critical link between perturbed tryptophan metabolism and dysregulated inflammation mediated by reduced AhR activation of microglia in glaucoma." (PMID 36754954, 2023). "In summary, our results illustrated the unbalanced tryptophan metabolism in glaucoma patients and the role of AhR signaling in retinal neuroprotection." (PMID 36754954, 2023). "Here, we collected serum and retina samples from glaucoma patients and non-glaucoma controls and detected significant decrease of serum tryptophan metabolites and reduced retinal AhR expression in glaucoma patients." (PMID 36754954, 2023). "In the current study, we propose that the development of glaucoma may involve the insufficiency of microglial AhR activation in retina, which may be resulted from altered tryptophan metabolism in glaucoma patients." (PMID 36754954, 2023). "Targeted metabolomics of human serum tryptophan signature revealed AhR related pathways were down-regulated, represented by decreased N-formyl-kynurenine and indole-3-propionic for kynurenine and indole pathways respectively in glaucoma patients." (PMID 36754954, 2023). "In the current study, although intraperitoneal injection was used to determine the protective role of tryptophan metabolites / AhR pathway in glaucoma, therapies focus on regulating this pathway could be various." (PMID 36754954, 2023). "We next investigated whether AhR signaling was involved in the development of glaucoma." (PMID 36754954, 2023). "Consequently, CYP1B1 expression, which is elevated during AhR activation, alters the biosynthesis of critical metabolites as well as metabolic pathways that may lead to the initiation and/or progression of glaucoma." (PMID 35743162, 2022). "Therefore, CYP1B1 expression, which is increased by AHR, alters production of critical metabolites and metabolic pathways that may lead to the development and/or progression of glaucoma." (PMID 35295218, 2022). "Therefore, we compared the retinal AhR expression of PACG patients and non-glaucoma controls, given that the great difficulty of acquisition of eyeball samples from POAG patients." (PMID 36754954, 2023). "While the up-regulated serotonin was also noted in glaucoma, which is not the widely reported AhR related pathway." (PMID 36754954, 2023). "Our patients did not exhibit any sign of glaucoma and no signs of glaucoma were reported in AHR-KO mice." (PMID 33193710, 2020). "In order to explore whether aryl hydrocarbon receptor (AhR) and its agonists tryptophan metabolites are involved in the development of glaucoma, we collected serum and retinas from non-glaucoma controls and patients with glaucoma." (PMID 36754954, 2023).
head and neck cancer (6 papers, 2020 to 2025). A primary or metastatic malignant neoplasm affecting the head and neck. "The beneficial effects of AhR ligands in colon cancer are well supported; however, AhR is also a pro-oncogenic factor in other tumor types, including head and neck cancer." (PMID 36769029, 2023). "For example, knockdown of the AhR in head and neck cancer cells decreases invasion and expression of growth-promoting genes such as amphiregulin, epiregulin and platelet derived growth factor A, demonstrating the pro-oncogenic activity of the AhR." (PMID 32932962, 2020).
head and neck squamous cell carcinoma (6 papers, 2014 to 2025). A squamous cell carcinoma that arises from any of the following anatomic sites: lip and oral cavity, nasal cavity, paranasal sinuses, pharynx, larynx, and salivary glands. "Also, a significant level of constitutive AhR activity was reported in cells isolated from head and neck squamous cell carcinoma (HNSCC) patients." (PMID 24755659, 2014).
hyperlipidemia (6 papers, 2017 to 2025). "Genotype frequencies of AhR rs2066853 reveal significant differences between CAD and control subjects, and hyperlipidemia and smoking significantly increased the risk of CAD associated with AhR polymorphism." (PMID 31638212, 2019). "In fact, AFB1 suppresses the expression of the aryl hydrocarbon receptor gene, resulting in the elevation of cholesterol observed in this study; hepatic lipase, encoded by the LIPC gene, is also suppressed by AFB1, contributing to hyperlipidemia." (PMID 40421175, 2025).
kidney damage (6 papers, 2019 to 2025). "This review systematically generalizes and summarizes various functions and signaling pathways of uremic toxin-activated AhR in current nephropathy studies." (PMID 38491448, 2024). "Here, we demonstrate that AhR−/− mice fed with an adenine-enriched diet had a low renal inflammation and fibrosis, suggesting that these mice are protected from 2,8-DHA nephropathy by mechanisms upstream of the renal injury and linked to adenine metabolism." (PMID 32260098, 2020). "In the current study, we found that AhR agonism by FICZ could attenuate kidney damage in rhabdomyolysis and ischaemia/reperfusion‐induced AKI." (PMID 33280241, 2021). "Mounting evidence has demonstrated that polyphenols, especially flavonoids, as modulators of AhR, are widely used for the regulation of the intestinal immune system and tumour treatment, but only several studies have reported that natural products regulate AhR in kidney damage." (PMID 31488157, 2019). "Here, we demonstrate that AhR knockout mice are also protected from 2,8-DHA nephropathy." (PMID 32260098, 2020).
liver inflammation (6 papers, 2019 to 2025). "Indole-3-acetic acid (IAA) promotes the expression of IL-22 and Reg3γ through the aryl hydrocarbon receptor (AHR), enhancing intestinal mucosal integrity and mitigating alcohol-induced liver inflammation." (PMID 40399593, 2025). "In the current study, therefore, we investigate by using TCDD, the role of AhR activation on a murine model of hepatitis." (PMID 35720411, 2022). "Because of the involvement of different types of immune cells during ConA-induced hepatitis, it is important to know the relative roles played by these cells in hepatitis and how AhR activation will impact these cell types." (PMID 35720411, 2022). "The use of TCDD, a potent AhR ligand also helped address the mechanisms through which AhR activation leads to attenuation of ConA-induced hepatitis." (PMID 35720411, 2022). "It maintained intestinal mucosa homeostasis by regulating intestinal flora and activating the microbiota aryl hydrocarbon receptor (AhR)-IL-22 axis, thus preventing and ameliorating liver inflammation and fibrosis." (PMID 35250597, 2022). "Also, AhR activation by TCDD attenuated ConA-induced hepatitis and additionally, reversed cellular and molecular changes brought about by ConA." (PMID 35720411, 2022). "Since HFD-related gut barrier dysfunction is a source of gut, VAT and liver inflammation and IR and AhR may have beneficial effects on the intactness of the gut epithelial barrier mediated by IL-22, we investigated similar immune-mediated mechanisms for indigo in glucose homeostasis." (PMID 30944419, 2019). "Indole-3-acetic acid (IAA), as a tryptophan catabolite and a microbiota-derived ligand of the aryl hydrocarbon receptor (AHR) which regulates AhR-dependent IL22 and Reg3g expression, strengthened the integrity of intestinal mucosa and reduced alcoholic-related liver inflammation." (PMID 37601074, 2023).
necrotizing enterocolitis (6 papers, 2020 to 2025). Necrotizing enterocolitis (NEC) is a devastating disease that affects mostly the intestine of premature infants. "The AhR ligand, indole-3- carbinole, activates AhR in the foetus and prevents development of the intestinal disease necrotizing enterocolitis in the offspring of mice." (PMID 37835602, 2023). "The anti-inflammatory effects observed in this study are in corroboration with recent findings demonstrating protection against necrotizing enterocolitis with ILA through AhR but here we provide evidence to also suggest a role for Nrf2." (PMID 33225894, 2020).
papillary thyroid carcinoma (6 papers, 2014 to 2021). "Abnormally high expression of aryl hydrocarbon receptor (AhR) has been implicated in dedifferentiation of radioiodine-refractory papillary thyroid cancer (RR-PTC)." (PMID 35002727, 2021). "Moreover, other studies demonstrated that papillary thyroid carcinomas overexpressed AhR with higher intensity in BRAF mutated samples." (PMID 31936153, 2020). "Clinicopathological features of patients with metastatic papillary thyroid cancer according to the expression of aryl hydrocarbon receptor (N = 32)." (PMID 35002727, 2021). "AhR expression was evaluated by quantitative polymerase chain reaction (qPCR) in 90 papillary thyroid cancers (PTCs), 11 medullary thyroid cancers (MTCs), and 6 anaplastic thyroid cancers (ATCs) and by immunohistochemistry (IHC) in a subgroup of 41 of the 90 PTCs." (PMID 31936153, 2020). "In most tumoral specimens in our series, AHR was abundantly expressed in the cytoplasm of papillary thyroid cancer cells and was instead absent in the normal adjacent tissue." (PMID 26392334, 2015).
pituitary tumor (6 papers, 2012 to 2025). A benign or malignant neoplasm affecting the pituitary gland. "DNA and RNA from pituitary tumor histological samples have been extracted and analyzed by PCR and direct sequencing for AHR gene variants, and compared with corresponding patients’ germline DNA as well as normal pituitary tissue as reference control." (PMID 33281746, 2020). "The aryl hydrocarbon receptor (AHR) pathway plays a critical role in the biology of Growth Hormone (GH)-secreting pituitary tumor (somatotropinoma)." (PMID 33281746, 2020). "It is known that the germline SNP rs2066853 may have an impact on AHR gene structure/function and that this polymorphism is more frequent among acromegaly patients and associated with a worse clinical outcome, biochemical profile and more invasive pituitary tumor." (PMID 33281746, 2020). "In vitro studies using GH3 cells were used to study the functional role of the AHR in pituitary tumours." (PMID 28649092, 2017). "AHR expression was found to be altered in one study with reduced immunohistochemical expression of AHR in pituitary tumours as compared to normal controls." (PMID 28649092, 2017). "Though only 20 high confidence variants were available for the signature analysis, this is not uncommon in pituitary tumours and the signature found raises the possibility of cooperation between the germline AHR and RXRG variants and somatic driver mutations." (PMID 31996203, 2020). "However, most cases of oncogenic AHR activity involve malignant forms of cancer, which differ significantly from pituitary tumour behaviour, which is benign in nature." (PMID 28649092, 2017). "However, no direct evidence has been found as yet linking the functional role of AHR in pituitary tumour formation or behaviour." (PMID 28649092, 2017). "Consequently, elevated and aberrant cAMP signalling, often seen in pituitary tumors, may imbalance AhR/ARNT and ARNT/Hif-1e signalling." (PMID 23300914, 2012). "The destabilization of AhR would naturally imbalance assembly of AhR/ARNT complex and it has been shown that levels of either ARNT or ARNT2, but not both, are devoid in AIP-deficient mouse pituitary tumors." (PMID 23300914, 2012). "In light of these considerations we speculated that in pituitary tumors of acromegaly patients with or without AHR/AIP germline genetic variants, this novel somatic deletion of AHR exon 10 (c.1246-1254) could contribute to alter the AHR pathway and favor tumor development." (PMID 33281746, 2020).
polycystic ovary syndrome (6 papers, 2022 to 2025). A disorder that manifests as multiple cysts on the ovaries. "The development of polycystic ovary syndrome is also associated with the Kyn-AhR pathway." (PMID 41282989, 2025). "Although hormonal and metabolic dysfunction have been recognized as a possible cause of polycystic ovarian syndrome (PCOS), the associations between hyperandrogenism and aryl hydrocarbon receptor (Ahr) signaling pathway remains controversial." (PMID 36368943, 2022).
renal carcinoma (6 papers, 2016 to 2025). A carcinoma arising from the epithelium of the renal parenchyma or the renal pelvis. "AF induced time-dependent AhR nuclear translocation and AhR transcriptional activity in sensitive renal cancer cell lines." (PMID 32443455, 2020). "Application of AhR inhibitor DMF could efficiently suppress distant metastasis of renal cancer cells, and improve anticancer effects of sorafenib (Sor)/sunitinib (Sun), which described a promising therapeutic strategy for clinical renal cancer." (PMID 33842334, 2021). "AF-cytotoxicity in human renal cell lines and a renal cancer cell strain was assessed by MTS assay in the presence or absence of an AhR inhibitor." (PMID 32443455, 2020). "Hypoxia-inducible factor (HIF) and aryl hydrocarbon receptor (AHR) are members of the bHLH-PAS family of transcription factors that underpin cellular responses to oxygen and to endogenous and exogenous ligands, respectively, and have central roles in the pathogenesis of renal cancer." (PMID 36725335, 2023).
thymus atrophy (6 papers, 2014 to 2026). Acquired diminution of the size of the thymus associated with wasting as from death and reabsorbtion of cells, diminished cellular proliferation, decreased cellular volume, pressure, ischemia, malnutrition, reduced function or malfunction, or hormonal changes. "Activation of the aryl hydrocarbon receptor (AHR) by the environmental toxin dioxin (2,3,7,8-tetrachlorodibenzo-p-dioxin, TCDD) causes diverse toxicities, including thymus atrophy and hepatosteatosis." (PMID 33320884, 2020). "In addition, PCB180 does not induce several of the characteristic AHR dependent responses, such as thymus atrophy, permanent body weight reduction, and the typical CYP induction profile." (PMID 25137063, 2014).